CDK4 (cyclin dependent kinase 4)
Diseases named in the same sentence as CDK4 in open-access papers (continued):
Sharing a sentence is not in itself a finding about the gene and the disease.
osteosarcoma (100 papers, 2000 to 2026). A usually aggressive malignant bone-forming mesenchymal neoplasm, predominantly affecting adolescents and young adults. "Age-specific patterns were observed, with Multi-TKI mutations more common in younger patients and CDK4/6 inhibitor mutations in adults, highlighting the need for personalized treatment approaches in osteosarcoma." (PMID 38841159, 2024). "Amplification of the MDM2 and CDK4 genes on chromosome 12 is commonly associated with low-grade osteosarcomas." (PMID 39322633, 2024). "Palbociclib showed efficacy in osteosarcomas with a loss of pRB function and/or the amplification of CDK4/6, whereas most other histologies were resistant." (PMID 37681936, 2023). "In osteosarcoma, the Rb/p16/CDK4 axis is often deregulated with mutations or deletions in these genes." (PMID 26807203, 2015). "CDK4 amplification and overexpression tend to be associated with better prognosis in the rarely occurring low-grade osteosarcomas but is associated with poor prognosis in the majority of osteosarcoma cases." (PMID 24835790, 2014). "For example, gain of chromosome 8q23 and CDK4 alone or together with MDM2 is associated with poor prognosis in osteosarcoma." (PMID 17439659, 2007). "Another subgroup of osteosarcoma patients that might benefit from CDK4/CDK6 inhibition, include patients with intact Rb, but loss of p16 expression." (PMID 34921235, 2022). "Taken together, our results illustrate that there is a clear subset of osteosarcoma patients (20–23%) for which CDK4/CDK6 inhibition might be promising and that loss of p16 protein expression or overexpression of CDK6, combined with intact Rb, may serve as a biomarker to select eligible patients." (PMID 34921235, 2022). "In this region are localized 2 genes, MDM2 and CDK4 which are often amplified in low-grade osteosarcomas and their proteins are found to be overexpressed." (PMID 40959149, 2025). "These insights are consistent with earlier findings, where MDM2 and CDK4 immunoreactivity aided in distinguishing low-grade osteosarcomas from benign fibrous dysplasia and TOS." (PMID 40926903, 2025). "Subsequent molecular analysis of the osteosarcoma tissue revealed homozygous loss of the CDKN2A gene locus, warranting treatment with CDK4/6 inhibitor palbociclib." (PMID 39820556, 2025). "Contrary, MDM2/CDK4 expression was reported rarely in conventional osteosarcoma and in primary and recurrent periosteal osteosarcomas." (PMID 40959149, 2025). "Group A comprised three low-grade osteosarcomas (one low-grade central and two parosteal) with amplification of CDK4 and MDM2, along with regions on chromosome arm 12p." (PMID 39322633, 2024). "Group C comprised seven conventional osteosarcomas displaying amplification of CDK4 and MDM2, along with numerous genome-wide copy number and structural variants." (PMID 39322633, 2024). "We selected osteosarcomas based on subtype or CDK4 and MDM2 status, drawing cases from two distinct cohorts." (PMID 39322633, 2024). "The authors found that all of the parosteal osteosarcoma samples demonstrated positivity to CDK4 gene amplification, and the majority showed positivity to MDM2 gene amplification." (PMID 38057715, 2023).
osteosarcoma (continued). "There is an ongoing clinical trial with Abemaciclib, an inhibitor of CDK4/6 for patients with chondrosarcoma and osteosarcoma (NCT04040205)." (PMID 37894336, 2023). "While CDK4/6 inhibitors have most evidence for treatment of LPS, a recent phase II study evaluated palbociclib for treatment of other types of STS and osteosarcoma with have high CDK4 expression and underexpressed CDKN2A mRNA." (PMID 36969064, 2023). "For example, AURKA was specifically expressed in proliferating osteoblastic osteosarcoma cells, while CDK4 was widely expressed in all subtypes of osteosarcoma cells." (PMID 37457661, 2023). "Our study demonstrates that 20–23% of primary osteosarcoma biopsies showed intact Rb, but defective p16 INK4A or overexpression of CDK4 and/or CDK6, indicating potential benefit from CDK4/CDK6 inhibition in almost one quarter of osteosarcoma patients." (PMID 34921235, 2022). "In osteosarcoma PDXs harboring pertinent molecular signatures, inhibition of CDK4/6 or BETs decreased growth." (PMID 36612255, 2022). "This is in line with other in vitro studies showing that pan-CDK or specific CDK4/CDK6 inhibition in osteosarcoma resulted in growth inhibition of cells and increased senescence and/or apoptosis." (PMID 34921235, 2022). "Inhibition of CDK4/6 or BETs decreased osteosarcoma PDX growth (two-way ANOVA, p < 0.05) confirming mechanistic involvement in growth." (PMID 36612255, 2022). "CDK4 is amplified in 10% of high-grade osteosarcomas, and together with CDK6 directly controls Rb activity by phosphorylation of Rb7–9." (PMID 34921235, 2022). "MDM2 and CDK4 immunohistochemistry has been shown to be a valuable tool in differentiating low-grade osteosarcomas from other primary fibro-osseous lesions of long bones." (PMID 35049602, 2021). "Cyclin D1 and CDK4 have also been reported to be overexpressed in osteosarcoma and related to its occurrence and development." (PMID 33321940, 2020). "Amplification of 12q13-15 region containing CDK4, MDM2, SAS and other potential oncogenes is present in 10% of osteosarcomas and is associated with ring chromosomes in parosteal OS." (PMID 32751922, 2020). "The expression of CDK4 in tumor tissues is specific and can provide a sensitive marker for diagnosis of low-grade osteosarcoma." (PMID 32117430, 2019). "Real time qPCR analysis of CDK4 showed a significant increase in its transcription in all osteosarcoma cell lines." (PMID 30220967, 2018). "In order to confirm that increased CDK4 and CDK6 activity results in RB hyperphosphorylation and leads to overexpression of HELLS, we treated all four human osteosarcoma cell lines with CDK4/6 inhibitor, palbociclib." (PMID 30220967, 2018). "CDK4/MDM2 co-amplification was predominant in parosteal osteosarcoma, and was also present in other subtypes consistent with previous reports." (PMID 28643781, 2017). "Amplification of CDK4 and loss of RB1, or CDKN2A loss are considered nearly universal in osteosarcoma with 20% of cases having either amplification of CDK4 or deletion of CDKN2A." (PMID 27074562, 2016). "The genetic inactivation of the Rb pathway, including the deletion of CDK inhibitors p16INK4A and the pocket protein Rb, as well as amplification of CDK4, is part of the reason why osteosarcoma cells are able to avoid permanent cell-cycle exit." (PMID 25853231, 2015).
osteosarcoma (continued). "CDK4 amplification and overexpression are commonly found in low-grade and dedifferentiated forms of osteosarcoma." (PMID 24835790, 2014). "Mouse double minute 2 (MDM2) and cyclin-dependent kinase 4 (CDK4) genes have been reported to be amplified or overexpressed in osteosarcoma, and these genes are thought to be involved in the pathogenesis." (PMID 18782081, 2008). "CDK4 gene is amplified in 9% of osteosarcoma tumours making this event significant in osteosarcoma pathogenesis as it can impact the RB pathway." (PMID 19506729, 2008). "Notably, this research revealed a therapeutic opportunity: CDK4/CDK6 inhibitors, like palbociclib, effectively target p16INK4A loss in osteosarcoma models." (PMID 40563473, 2025). "In addition, immunohistochemical analysis of murine double-minute type 2 and cyclin-dependent kinase 4 (CDK4) can help to distinguish low-grade osteosarcoma from benign histological imitators, since FLs do not express them." (PMID 38544774, 2024). "Therefore, we investigated the sensitivity to CDK4/CDK6 inhibitor palbociclib in osteosarcoma cells." (PMID 34921235, 2022). "Alterations in the Rb/p16 pathway could indicate that osteosarcoma cells are vulnerable to CDK4/CDK6 inhibitor treatment." (PMID 34921235, 2022). "Indeed, using two-dimensional (n = 7) and three-dimensional (n = 3) cultures of human osteosarcoma cell lines, it was shown that osteosarcoma cells with defective p16INK4A are sensitive to the CDK4/CDK6 inhibitor palbociclib after 72-hour treatment." (PMID 34921235, 2022). "Indeed, CDKN2A is deleted in 22% of osteosarcomas and CDK4 is amplified in 28% of oral melanomas, resulting in frequent cell cycle gene alteration in both tumor types." (PMID 34344882, 2021). "Furthermore, two out of these three (cases 1 and 4) showed nuclear immunoreactivity to MDM2 and CDK4, indicating their compatibility with low‐grade osteosarcoma." (PMID 34008925, 2021). "It has been reported in many other cancers that CDK4 amplification could drive resistance to chemotherapy, including osteosarcoma and breast cancer." (PMID 34750392, 2021). "In addition, the finding of MDM2 and/or CDK4 amplification/overexpression in a high-grade osteosarcoma indicates progression/dedifferentiation from a low-grade osteosarcoma and practically excludes a primary conventional high-grade osteosarcoma." (PMID 33799733, 2021). "CDK4 is amplified in 67% of parosteal osteosarcomas, but rarely in high-grade osteosarcoma (9%)." (PMID 31741049, 2020). "As the percentage of CDK4 and MDM2 amplifications in low-grade central osteosarcoma and parosteal osteosarcoma are much higher than in high-grade osteosarcoma, most likely the CDK4/MDM2 amplified high-grade tumours represent progression from low grade osteosarcoma." (PMID 31741049, 2020). "However, CDK4/6 inhibition (Abemaciclib) have been reported widely in several cancers such as Neuroblastoma Ewing sarcoma, Rhabdomyosarcoma, Osteosarcoma." (PMID 32033228, 2020). "The enhanced expression of the cyclin D/CDK4/Rb pathway inevitably contributed to the rampant survival and proliferation of cancer cells within a large variety of malignant categories, especially osteosarcoma and synovial sarcoma." (PMID 30808351, 2019). "Whether EEF1D directly or indirectly affects CyclinD1/Cdk4 or Cyclin B1/Cdk1 activity in osteosarcomas remains to be investigated." (PMID 29510727, 2018).
osteosarcoma (continued). "However, new findings in immunohistochemistry with determination of MDM2 and CDK4 markers show promising results in distinguishing parosteal osteosarcoma from benign clinical and histological mimics." (PMID 24066980, 2013). "Interestingly, CDK4 is also prominent in this circuit, which is a primary inhibitor of the tumor suppressor pRb, which is also frequently abnormal in spontaneous human osteosarcoma." (PMID 23890326, 2013). "For confirmation, the pathological samples removed in May 2004 were collected for re-examination, and notably for molecular analysis of MDM2 and CDK4 oncogenes, whose amplification had been reported in low-grade intraosseous and parosteal osteosarcomas." (PMID 21106072, 2010). "Group B included ten osteosarcomas, spanning low- and high-grade cases (three parosteal, two low-grade central, three dedifferentiated parosteal, and two conventional), all displaying amplification of CDK4 and MDM2, along with regions on chromosome arm 12p in all but three cases." (PMID 39322633, 2024). "Our results illustrate that loss of CDKN2A and/or CDKN2B are early events in the development of osteosarcoma, and that these events can be targeted by CDK4/CDK6 inhibition, which might be used as a novel therapeutic option in approximately 20–23% of the patients." (PMID 34921235, 2022). "Thus, our data support previous findings that CDK4/CDK6 inhibition might be a new targeted treatment strategy for osteosarcoma patients." (PMID 34921235, 2022). "Luckily, RB1 and CDK4 mutations seem to be mutually exclusive in osteosarcomas and thus CDK4/6 inhibition may be applied without fear of reverting mutations, although they could occur as a response to multimodal chemotherapy." (PMID 33963544, 2021). "Therefore, the MDM2 and CDK4, usually amplified in low‐grade osteosarcomas, might be key molecules involved in the tumorigenesis of low‐grade osteosarcomas." (PMID 34008925, 2021). "Regarding oncogenes, amplification of MDM2 and CDK4 is commonly observed in WDLPS, DDLPS, ALT, dedifferentiated parosteal osteosarcoma, and osteosarcoma NOS." (PMID 40141463, 2025). "Frequent genomic aberrations of CDK4/6 in rhabdomyosarcoma, osteosarcoma, and other pediatric tumors were documented by means of the target actionability review (TAR) methodology to assess data on CDK4/6 as a therapeutic target in pediatric solid tumors." (PMID 41514647, 2025). "In this study, we conducted comprehensive genomic and transcriptomic analyses on both high- and low-grade osteosarcomas exhibiting MDM2 and/or CDK4 amplification and verified our findings using longread whole-genome sequencing." (PMID 39322633, 2024). "Selective amplification of CDK4 and MDM2 is a particularly common phenomenon in low-grade osteosarcoma." (PMID 39322633, 2024). "In this study, we conducted high-resolution genomic and transcriptomic analyses on 33 samples from 25 osteosarcomas, encompassing both high- and low-grade cases with MDM2 and/or CDK4 amplification." (PMID 39322633, 2024). "Amplification of CDK4 and MDM2 was found in 67% of parosteal osteosarcoma that is a low-grade differentiated type of osteosarcoma and in 9–12% of classical osteosarcoma." (PMID 36611942, 2022). "As the efficacy of CDK4/CDK6 inhibition relies on the presence of intact Rb, the Rb status of each osteosarcoma cell line was determined by Western blot." (PMID 34921235, 2022). "In Osteosarcoma (OS) cells, miR-338-3p acts as a tumor suppressor by targeting runt-related transcription factor 2 (RUNX2) and CDK4, which inhibits the MAPK pathway." (PMID 36233210, 2022).
osteosarcoma (continued). "For osteosarcoma cells, miR-338-3p inhibits RUNX2/CDK4 expression and the MAPK signaling pathway to inactivate tumor cells proliferation and metastasis." (PMID 34718336, 2021). "Case 7 presented with a conventional high‐grade osteosarcoma, however, the presence of low‐grade osteosarcoma components and the MDM2 and CDK4 immunoreactivity suggests that the patient had progressed from low‐grade osteosarcoma." (PMID 34008925, 2021). "Functional experiments and mechanistic studies revealed that circ_001621 promoted the proliferation and migration of osteosarcoma cells in vitro via attenuating miR‐558‐mediated repressing of VEGF and the downstream expression of CDK4 and MMP9." (PMID 33103338, 2021). "MiR‐145‐5P inhibits osteosarcoma cell proliferation by targeting inhibit of E2F3b, which affected Cyclin D1, CDK2, CDK4 and CDK6 expression." (PMID 34741389, 2021). "Our experiments also suggested that both CDK4/6 inhibitor Palbociclib and AKT inhibitor Perifosine have an antiproliferation effect on osteosarcoma in vitro." (PMID 34185412, 2021). "Low-grade osteosarcomas can transform into high-grade osteosarcomas and still preserve the amplification of chromosome 12q and overexpression of MDM2 and CDK4." (PMID 35049602, 2021). "CDK4 and CDK6 amplification and overexpression has been reported in some osteosarcomas, resulting in RB hyperphosphorylation." (PMID 30220967, 2018). "Here, we detected upregulation of CDK4 and/or CDK6 mRNA levels in all osteosarcomas, which suggests a predominant mechanism of RB-E2F pathway inactivation through RB hyperphosphorylation in this malignancy." (PMID 30220967, 2018). "Suppression of miR-506-3p in osteosarcoma led to increased expression of RAB3D, which in turn led to increased CDK4 (cyclin-dependent kinase 4) and MMP9 (matrix metalloprotein 9) activities." (PMID 29905536, 2018). "Our results suggest that miR-506-3p acts as a tumor suppressor in osteosarcoma and that its downregulation leads to tumor cell proliferation and metastasis due to upregulation of RAB3D- and CDK4-mediated signaling." (PMID 29905536, 2018). "To investigate the underlying molecular mechanism of baicalein on cell cycle regulation, we examined the expression levels of Cyclin D1, Cyclin E1, CDK4, CDK6, c-myc, pRb, p21 and p27 in osteosarcoma cells, which treated with different doses of baicalein." (PMID 29156780, 2017). "The second hotspot, located in 12q, was rearranged in four osteosarcomas (samples 1, 8, 9, 10) and coincided with the genes MDM2 and CDK4." (PMID 25300797, 2014). "Amplification of genes in the 12q13-15 region, such as SAS, CDK4 and MDM2, is relatively frequent in osteosarcoma, notably in low-grade parosteal OS, making them suitable as markers for distinguishing them from benign ossifying." (PMID 21106072, 2010). "Pervious studies have shown the amplification GLI, CHOP, SAS, HMGI-C, CDK4, HDM2, and PRIM1 from 12q13-q15 region in osteosarcoma." (PMID 15298715, 2004). "Thus, co-amplification of CDK4/MDM2 and the presence of ring chromosomes supported even stronger diagnosis of parosteal osteosarcoma." (PMID 40959149, 2025). "They found that all benign fibro-osseous lesions were negative for MDM2 and CDK4, while 89% of low-grade osteosarcomas were positive for both tests." (PMID 39105970, 2024). "This can be exploited with a CDK4/CDK6 inhibitor, as osteosarcoma cells showed sensitivity to palbociclib which might be used as a novel therapeutic option." (PMID 34921235, 2022). "In the current study sensitivity to palbociclib did not correlate with CDK4 expression in osteosarcoma cells." (PMID 34921235, 2022). "Western blots showed that 24 h DFO and DFX treatment markedly decreased the expression of cyclin D1 and cyclin-dependent kinase 4 (CDK4) in osteosarcoma cells, but CDK4 expression not significantly decreased in K7M2 cell." (PMID 34281233, 2021).